CCL18 (C-C motif chemokine ligand 18)
Diseases named in the same sentence as CCL18 in open-access papers (continued):
Sharing a sentence is not in itself a finding about the gene and the disease.
lung cancer (19 papers, 2010 to 2025). A malignant neoplasm involving the lung. "In lung cancer, TAM-derived CCL18 is thought to promote metastasis by facilitating the migration of lung cancer cells." (PMID 39114657, 2024). "The elevated expression of CCL18 protein lung cancer cells was further confirmed by Western blot analysis." (PMID 36217054, 2023). "To this end, we initially examined the expression of CCL18 in 95C, 95D, A549, and H460 lung cancer cell lines." (PMID 36217054, 2023). "Meanwhile, we found that treatment with DHA and EPA robustly reduced CCL18 expression in A549 and 95D lung cancer cells, whereas the inhibitory effect of DHA was also more pronounced than that of EPA." (PMID 36217054, 2023). "According to our results, the mRNA levels of CCL18 were significantly increased in lung cancer cells relative to the normal lung epithelial cells." (PMID 36217054, 2023). "We further observed an MDM subset expressing inflammation and phagocytosis-associated genes (cluster 4; CCL18, IL18, C1QA and TREM2) and enriched for samples from patients with COVID-19 pneumonia, as well as samples from patients with lung carcinoma." (PMID 37291214, 2023). "We already demonstrated that serum levels of CCL18, a primate specific chemokine, are highly elevated in patients with lung cancer and correlate with their survival time of patients with adenocarcinoma of the lung." (PMID 23349697, 2013). "Exposure of A549 lung cancer cells to CCL18 in various concentrations decreases the epithelial marker E-cadherin, whereas FSP-1, a marker of the mesenchymal phenotype increases." (PMID 23349697, 2013). "We observed that CCL18 exerts a dose dependent increase in chemotaxis of lung cancer cells indicating, that CCL18 attracts lung cancer cells to sites of CCL18 release." (PMID 23349697, 2013). "We observed that the mean serum level of CCL18 in patients with lung cancer is more than four fold increased compared with healthy controls." (PMID 22848587, 2012). "Here CCL18 was measured in sera of 31 healthy volunteers and 170 patients with lung cancer and correlated these data with histology, tumor stage and clinical parameters." (PMID 22848587, 2012). "CCL18 is a cytokine released from tumor-associated macrophages that binds to CCR8 and has been implicated in the epithelial-mesenchymal transition of breast, pancreatic and lung cancers." (PMID 29100308, 2017). "CCL18 also accelerated cell invasion and metastasis in breast and lung cancer cells." (PMID 26919103, 2016). "Chemotherapy of NSCLC still relies on platinum derived drugs although it is known that several mechanisms exist how lung cancer cells escape cisplatin cytotoxicity and CCL18 might be a pivotal mediator in these processes." (PMID 23349697, 2013). "The presence of highly elevated CCL18 serum levels in patients with non-small-cell lung cancer could point to an important role of CCL18 in the microenvironment of lung cancer and might be a potential target in the therapy of lung cancer." (PMID 22848587, 2012). "Therefore we investigated the serum level of lung cancer patients with non-small-cell lung cancer and the correlation of CCL18 to clinical parameters." (PMID 22848587, 2012). "Interestingly, the CCL18 serum levels differed according to the histological subtype of lung cancer." (PMID 22848587, 2012). "Of note, the expression level of CCL18 was significantly higher in the high-metastatic lung cancer cells 95D than that in the low-metastatic lung cancer cells 95C, suggesting that CCL18 expression might be closely related to the invasion and metastasis capability of lung cancer cells." (PMID 36217054, 2023). "Thus, we conclude that CCL18 will be a future target in the treatment of lung cancer." (PMID 23349697, 2013). "Therefore, we hypothesized that CCL18 may be directly involved in pathological processes of lung cancer, e.g. EMT." (PMID 23349697, 2013).
lung cancer (continued). "In addition, it has been shown that TAM release CCL18 which brought us to the hypothesis that CCL18 might serve as a serum biomarker in patients with lung cancer." (PMID 22848587, 2012). "Moreover, the comparison with other cancers like cervical squamous cell carcinoma, colon cancer, and lung cancer suggests that these methylation patterns may be specific to BRCA, pointing to a potential mechanism underlying the upregulation of CCL18 and EGF in breast tumorigenesis." (PMID 40692603, 2025). "Remarkably, CCL18 exhibited significant promoter hypomethylation not only in BRCA but also across cervical, colon, and lung cancer tissues." (PMID 40692603, 2025). "Our previous studies showed that CCL18 is highly expressed in NSCLC tissues and the serum of lung cancer patients, whereby its expression levels were positively correlated with a late clinical stage and lymph node metastasis of NSCLC." (PMID 36217054, 2023). "MPE-Mφ showed relatively higher expression levels of M1 (IL-1β, IL-6, and CXCL10), M2 (CCL18 and IL-10), and pan-macrophage markers (CSF1 and PTPRC) compared to MDMs from lung cancer patients or HCs." (PMID 33175182, 2021). "In addition to CCL18, CXCL12 and CCL22 are known to alter the TME in lung cancer by modulating TAM activity." (PMID 39114657, 2024). "EV-miR-103a from hypoxic lung cancer cells enhances M2 macrophage polarization by targeting PTEN, which further promotes the migration and invasion of lung cancer cells and tube formation of HUVECs by secreting IL-10, CCL18 and VEGF- A." (PMID 32503543, 2020). "USP17 could be induced by cytokines secreted from macrophages because various cytokines, including TNF-α, IL-1β, IL-4, IL-6, IL-8, IL-10, CXCL12, CCL18, and CCL22, were able to induce USP17 expression in H1299 and D121 lung cancer cells." (PMID 30038267, 2018). "Interestingly, comparing to the MDMs from HCs, some cases of lung cancer patients’ MDMs showed MPE-Mφ-like patterns on elevating expression levels of CXCL10, CCL18, and MRC1, may indicate the local and systemic effects of the tumor microenvironment." (PMID 33175182, 2021). "Given that DHA significantly inhibited cellular CCL18 expression, and simultaneously, the invasion and migration capability of NSCLC cells, we then determined whether downregulation of CCL18 expression is directly involved in DHA-mediated suppression of lung cancer cell metastasis." (PMID 36217054, 2023).
pancreatic cancer (17 papers, 2015 to 2025). "Previous studies have reported that CCL18 released by TAMs promotes pancreatic cancer growth and metastasis, causing poor survival of PDAC patients." (PMID 29670110, 2018). "To identify and quantify the amount of infiltrated TAMs with the M2 phenotype, we tested the expression of CCL18, the hallmark of TAMs in paraffin-embedded pancreatic cancer samples by immunohistochemistry (IHC)." (PMID 29670110, 2018). "TAMs secrete cytokines and chemokines, such as CCL18, which upregulates VCAM-1 in pancreatic cancer via the CCL18/PITPNM3/NF-κB/VCAM-1 pathway, promoting tumor progression." (PMID 40443678, 2025). "Macrophage-derived CCL18 also enhances the invasive ability of pancreatic cancer cells by inducing VCAM-1 expression." (PMID 34201127, 2021). "Here, we show that CCL18 secreted by TAMs facilitates malignant progression and induced a glycolytic phenotype in pancreatic cancer, partially owing to paracrine induction of VCAM-1 in pancreatic cancer cells." (PMID 29670110, 2018). "Our results showed that the expression of CCL18 level in pancreatic cancer was significantly higher than that in corresponding normal pancreatic tissues." (PMID 29670110, 2018). "Our results confirmed that the expression level of CCL18 in pancreatic cancer was significantly higher than that in corresponding normal pancreatic tissues and that CCL18 is the most abundantly expressed cytokine in IL-4-activated M2 macrophages." (PMID 29670110, 2018). "In conclusion, we demonstrated that CCL18-positive TAMs were important in malignant progression and induced a glycolytic phenotype in pancreatic cancer, partially owing to paracrine induction of VCAM-1 in PDAC cells." (PMID 29670110, 2018). "In pancreatic cancer cells for example, CCL18 is expressed both by tumor cells and by M2‐polarized macrophages." (PMID 28599100, 2017). "A recent pathway-based analysis of pooled GWAS data reported that T-helper (Th) immune response genes (Th1/Th2), such as transforming growth factor-beta receptor 2 (TGFBR2), chemokine ligand 18 (CCL18), and IL13RA2, were associated with pancreatic cancer risk." (PMID 25945796, 2015). "In this study, our work provides the valid evidence for reciprocal signaling interactions between TAMs and pancreatic cancer cells, shedding new light on the utilization of CCL18/PITPNM3/NF-kB/VCAM-1 axis as a potential novel therapeutic target for the treatment of pancreatic cancer." (PMID 29670110, 2018). "Macrophage-derived cytokines and chemokines including IL1β, CCL18, and IL8 can promote the epithelial-mesenchymal transition of pancreatic cancer cells through various signaling pathways, including PAR1 and TLR4/IL10 activation." (PMID 34201127, 2021). "Our study provides the first connection between CCL18/PITPNM3/NF-kB/VCAM-1 axis and PDAC progression and the Warburg effect, raising the possibility of new options for clinical interventions for pancreatic cancer patients." (PMID 29670110, 2018). "In vitro, recombinant CCL18 induces migration, and invasion, as well as EMT‐TF Snail1 expression in pancreatic cancer cell lines." (PMID 28599100, 2017). "In pancreatic cancer, TAM-M2 cells have been found to enhance aerobic glycolysis in pancreatic cancer cells, thereby promoting tumor invasion and metastasis via the secretion of the chemokine CCL18, which interacts with its receptor, PITPNM3." (PMID 39227970, 2024). "For human pancreatic ductal adenocarcinoma (PDAC), serum CCL18 is a potential biomarker of diagnosis and prognosis and have been found promoting the epithelial–mesenchymal transition (EMT), invasion, and migration of pancreatic cancer cells." (PMID 35609322, 2022).
COVID-19 (14 papers, 2020 to 2025). A disease caused by infection with severe acute respiratory syndrome coronavirus 2. "An elevated level of CCL18 is associated with inflammation in the lungs of COVID-19 patients through the recruitment and activation of immune cells, including T-cells and dendritic cells in the lungs." (PMID 39040605, 2024). "Like SPP1, CXCL10, and CCL2, whose plasma levels associate with COVID-19 severity, the plasma level of CCL18 was also found to be significantly different between patients with mild and critical COVID-19." (PMID 37917179, 2023). "Here the authors spatially associate CCL18 and CCL21 in distinct tissue niches with lung pathology of severe COVID-19." (PMID 36774347, 2023). "In this study, we demonstrate that CD163+ macrophages accumulating in COVID-19 lungs produce CCL18 and spatially allocate this chemokine to the fibrotic patches." (PMID 36774347, 2023). "Single nuclei RNA sequencing (snRNAseq) data obtained from some of the same samples and donors 23 confirmed that CD163+ macrophages in COVID-19 are the cellular source of CCL18." (PMID 36774347, 2023). "The macrophage population upregulated CD163 in COVID-19 lungs compared to controls, and showed an enrichment of CCL18 expression in later disease phases compared to the acute lungs." (PMID 36774347, 2023). "In line with our findings, CD14hiCD16hi cells and AMs enriched with viral RNA in autopsy lungs of COVID-19 patients also had distinct transcriptomes which were largely recapitulated in what we construe as CXCL10-associated genes (CXCL11, CCL18, CCL8, ISG15, CD83)." (PMID 35483404, 2022). "Our analysis suggests that CCL8, CCL18, and other chemokine receptor binding are enriched in the gene expression profile of patients who suffered COVID-19 and COPD, which may contribute to the high rate of severe illness and mortality." (PMID 35747501, 2022). "Indeed, knock-down of MAFB prior to SARS-CoV-2 exposure significantly reduces the expression of chemokines that stimulate fibrosis (CXCL13, CCL18) and neutrophil recruitment (various CXCL chemokines), 2 processes that are closely linked to COVID-19 severity and post–COVID-19 pulmonary sequelae." (PMID 37917179, 2023). "Macrophages from patients with IPF and COVID-19 were both found to express fibrosis-associated genes including Secreted Phosphoprotein 1 (SPP1), transforming growth factor beta 1 (TGFB1), transforming growth factor beta-induced (TGFBI), legumain (LGMN), and C-C Motif Chemokine Ligand 18 (CCL18)." (PMID 37759460, 2023). "Research has found that, compared to a control group, serum levels of PARC/CCL18 and GNLY (granulysin), as well as IgG levels against MX1 and METTL3, are elevated in patients with AA related to the COVID-19 vaccine." (PMID 39021569, 2024). "Alongside, we observed a high expression of cytokines (CCL3, CCL4, CCL5, CCL7, CCL18 and CCL20) in the CD4+ TCM, Classical monocytes and NK cells in the COVID-19 patients." (PMID 36532041, 2022). "The prominent M2 Mac (C1QA+CCL18+), and M0 Mac (CD68+CD163lowITGAM+) were enriched in normal controls compared to COVID-19 patients." (PMID 34238338, 2021). "While some genes involved in monocyte and lymphocyte migration and function were expressed in the COVID-19(+) TV group (CCL13, CCL8, and CCL20), a greater number of these genes were expressed in the COVID-19(-) PU control group (CCL19, CCL18, CXCL13, CCL4, CCL5, CXCL9)." (PMID 37026002, 2023). "Specifically, signatures of plasma cells (IGHG3, IGKC, IGHM, JCHAIN, IGHG2, IGKV4-1, IGLV3-1, IGHA1), activated fibroblasts (COL1A1, COL1A2, COL3A1), inflammatory cytokines (CXCL9, CCL18) and complement factors (C1QB, C1QC) dominated the DE genes for the COVID-19 lung sections." (PMID 37858234, 2023).
glioma (14 papers, 2020 to 2025). A benign or malignant brain and spinal cord tumor that arises from glial cells (astrocytes, oligodendrocytes, ependymal cells). "Using a humanized glioma model, CCL18 was recently demonstrated to drive glioma progression via CCR8-ACP5 signaling." (PMID 40835683, 2025). "And, CCL18 enhances the invasion and proliferation of U251 glioma cells." (PMID 35985661, 2022). "A recent study indicate that CCL18 derieved from TAMs are vital in promoting glioma progression." (PMID 36177003, 2022). "Oxamate treatment decreased Ccl1 and Ccl8 expressions of tumor tissues from glioma implanted nude mice, consistently, CCL1 and CCL18 levels in cultured THP-1 cells in vitro were increased by lactate." (PMID 37770937, 2023). "HIF-2α inhibition may regulate the recruitment of Tregs to the glioma site through a reduction of Treg-attracting chemokines such as CCL17, CCL22, and CCL18 or a re-polarization of the pro-tumoral macrophages secreting these factors." (PMID 40095115, 2025). "As such, the glioma growth-promoting cytokine, CCL18, is expressed by human microglia, but not by murine microglia." (PMID 37990867, 2023). "The research team found that there was an upregulation in IL-10, Osteopontin, MMP14, VEGF, TGF β, and CCL18 in samples containing both human stem cell derived microglial cells with human glioma cells, as opposed to samples containing human glioma cells alone." (PMID 36700223, 2022). "Among the 10 candidates, high mRNA expression of CCL8, FCGR2B, and TUBA4A and low mRNA expression of GABRD, PRAME, and SYN1 were significantly correlated with worse prognosis, while the mRNA expression of CCL18, SCN1B, SNCB, and VSNL1 showed no connection to the overall survival of glioma patients." (PMID 36685974, 2022).
colorectal cancer (13 papers, 2016 to 2025). A primary or metastatic malignant neoplasm that affects the colon or rectum. "In these enriched pathways, colorectal cancer signaling pathway, ranking in the first place, includes 12 DEGs caused by CCL18 stimulation, which is involved in cancer initiation and progression." (PMID 30181713, 2018). "In colorectal cancer liver metastases, highly metabolically active MRC1+CCL18+ M2 macrophages have been identified and are associated with poor response to neoadjuvant chemotherapy." (PMID 40612672, 2025). "For example, MRC1+ CCL18+ macrophages in colorectal cancer show enrichment in oxidative phosphorylation, while macrophages in liver metastasis primarily rely on amino acid metabolism." (PMID 39015576, 2024). "For colorectal cancer, CCL18 expression level is also an independent favorable prognostic biomarker." (PMID 35609322, 2022). "The pathways include: WP4239 (EMT in colorectal cancer), WP5097 (CCL18 signaling that led to EMT or migration and invasion), and WP5469 (Hallmark of cancer: metastasis and EMT)." (PMID 40679044, 2025). "Chemokines, including CXCL10, CXCL12, CX3CL1, CCL2, CCL5, CCL18, and CCL20, induce chemotaxis to promote cell migration and invasion in ovarian, lung, breast, and colorectal cancers." (PMID 38438872, 2024).